CD4 (CD4 molecule)
Diseases named in the same sentence as CD4 in open-access papers (continued):
Sharing a sentence is not in itself a finding about the gene and the disease.
tumor (continued). "The immune-inflamed phenotype is characterized by the presence of CD4+ T, CD8+ T, myeloid, and monocytc cells in the TME, which is positioned near the tumor cells." (PMID 35372339, 2022). "In the early stage of tumor development, TANs upregulate the expression of costimulatory molecules OX-40L and 4-1BBL to enhance the T cell immune response and increase the cytotoxicity of CD4+ T cells and CD8+ T cells, to exhibit “tumor inhibition” functions." (PMID 35493517, 2022). "Both CD4+ Th9 and CD8+ Tc9 cells exhibit a superior ability to control tumor growth compared to their Th1 or Th17 counterparts." (PMID 35203357, 2022). "We also analyzed tumor CD3+, CD4+, and CD8+ T-cell and FOXP3+ cell percentages via immunofluorescence staining." (PMID 36212401, 2022). "Of the CD4 T cells that managed to infiltrate the flank tumor in the ENI mice, fewer were OVA-specific compared to mice treated with tumor only SBRT." (PMID 36385142, 2022). "Accordingly, 19.4% and 18.7% of the overall number of CD4+ and CD8+ lymphocytes, respectively, were located at vascular sites where a higher CD4-to-CD8 ratio (1.15) compared to that observed at tumor site (IT, 0.89) was detected." (PMID 35805021, 2022). "Tumor microenvironment analysis showed that FUBP3 expression was positively correlated with the expression of CD8+ T cells, CD4+ T cells, and macrophages (P < 0.05)." (PMID 35413821, 2022). "Researchers have reported that CD40LG has a potent anti-tumor effect, which can be attributed to the CD40L–CD40LG interactions and can induce anti-tumor immunity by eliminating tumor-specific CD4+ and CD8+ tolerance." (PMID 36276933, 2022). "More CD4+ and CD8+ T cells accumulated in tumour tissues, and CD8+ T cells had lower expression of checkpoint molecules such as lymphocyte activation gene 3 protein (LAG‐3) and programmed cell death protein 1 (PD‐1)." (PMID 35665592, 2022). "The analysis presented that expression of CD4+ T cells in residual tumors and IFN-γ generation in response to tumor cells were considerably higher in mice treated with anti-CTLA-4 than in the control group." (PMID 35392976, 2022). "A consistent trend was also observed when analysed on CD4+ T and CD8+ T cells separately, where Treg markers and exhaustion markers were found to be enriched in S2 tumours respectively; while the proinflammatory gene GZMB was depleted in S2 tumours." (PMID 35301339, 2022). "MSN-L shows:Prominent tumor growth inhibition;Enhanced OVA-specific CD4+, CD8+T lymphocyte activation and maturation." (PMID 35748543, 2022). "On the other hand, cytotoxic CD8+ T cells are crucial components of tumor-specific cellular adaptive immunity as T­helper (TH) 1, TH17, CD4+ T cells and Natural Killer cells are in the tumor microenvironment are." (PMID 36741710, 2022). "We showed that effective anti-tumor responses required a subset of tumor-infiltrating CD8+ and CD4+ T cells." (PMID 36365247, 2022). "In contrast, biomarkers of T cell subset, CD3, CD4, and CD8, were highly expressed in the normal lung tissues and stage I adenocarcinoma tissues but significantly reduced in the stage II and III tumor tissues." (PMID 35187162, 2022). "In line with this, the ratio between CD4+ and CD8+ T cells was significantly higher in the tumor nest and 20 μm and 50 μm from the tumor compared to the total stroma." (PMID 35954489, 2022). "In tumor-adjacent normal tissue, CLDN18.2-postive showed a distinct tumor microenvironment with higher CD4+ FoxP3+ Treg immune cells and CD4+PD-L1+ T cells." (PMID 35811317, 2022). "These higher CD45+ immune infiltrates induced by the MuSyC-dose treatment led to an enhanced percentage of CD8+ T cells, CD4+ T cells, NK cells, and CD68+ MACs in the tumor compared to the other groups." (PMID 36059502, 2022). "This virus shows treatment efficacy, but lacks additional payloads that we have shown here can significantly boost CD4+ and CD8+ T cells, especially memory T cell subtypes, which provide long-term robust anti-tumor immunity." (PMID 35795092, 2022).
tumor (continued). "CD4 + T cells and CD8 + T cells can activate the immune system to kill tumor cells, a research hotspot in tumor immunotherapy." (PMID 35397536, 2022). "Cooperative CD4+ and CD8+ T cell interactions, facilitated by NDV-induced IFN-I, then lead to the establishment of tumor-specific adaptive immune reactivity and systemic protective immunological memory." (PMID 35327364, 2022). "Correlation analysis of six prognostic MDGs (ABCG1, KDF1, KITLG, TGFA, HAVCR2, and CD14) and six types of immune infiltrating cells, including tumor purity, B cells, CD8+T cells, CD4+T cells, macrophages, neutrophils, and dendritic cells was performed." (PMID 35774505, 2022). "By increasing the infiltration of CD3+/CD4+ T cells and DX5+ NK cells in the tumor area, the expression of cytokines such as IL-1β, TNF-α, IFN-γ, GM-CSF were increased, and the anti-tumor effect was also observed." (PMID 35757741, 2022). "The TME accumulation of both CD4+ and CD8+ cells confined to tumor areas with normalized vessels is established, although the overall number of T cells in the tumor mass remains unchanged, indicating the importance of normalization for ImT." (PMID 36276103, 2022). "The immune effector components, including B cells, CD4+ T cells, and CD8+ T cells, were decreased in the tumor environment of patients with high mrDEGPS." (PMID 35794182, 2022). "Although CD4+ and CD8+ T cells were high in the RelB-KO group, the cell numbers declined as PD-L1 expression increased in tumour cells." (PMID 35177112, 2022). "A large number of T cells were infiltrated in the tumor biopsies of some patients, including CD8+ T cells and CD4+ T cells." (PMID 35892835, 2022). "T-cell activity was evaluated by isolating tumor-specific CD8+ T-cells and measuring the production of cytokines (IFN-γ and IL-2) by CD8+ and CD4+ T-cells challenged with MCPyV peptides." (PMID 35743435, 2022). "Recently, TGF-β was found to suppressed T helper 2-cell-mediated cancer immunity, targeting TGF-β signaling blockade in CD4+ T cells is a novel way to remodel TME and restrict tumor progression." (PMID 36317140, 2022). "DCs can present antigen through MHC I and MHC II molecules and activate CD4+T and CD8+T, which can activate specific anti-tumor immune response, so as to make tumor recede." (PMID 35795680, 2022). "The immunoreactivity of CD3, CD4, CD5, CD8, and PD-1 was analysed immunohistochemically in tumor-infiltrating lymphocytes (TILs) and stromal lymphocytes." (PMID 36514573, 2022). "In both cases, surgically resected patients achieved long-term survival, and significant infiltration of CD4+ and CD8+ T cells was detected either in fibrosis near the residual cancer cells or in the resected tumor specimen." (PMID 36091031, 2022). "CD4+ helper T cells and CD8+ cytotoxic T cells are in close contact with tumor cells, which have critical effects on tumor immunity." (PMID 35769818, 2022). "In conclusion, more investigative efforts are needed to dissect the phenotypic and functional heterogeneity of CD4+ TRM cells and to better understand their role in anti-tumor immunity." (PMID 36385379, 2022). "In the adaptive immune system, CD4+ T cells and dendritic cells (DCs) are important mediators, while CD8+ cytotoxic T lymphocytes (CTLs) play the ultimate tumor-killing role." (PMID 36532071, 2022). "Tumor oncolysis and release of PAMPs and DAMPs, which are recognized by pattern recognition receptors (PRR), lead to DC activation and subsequent CD4 and CD8 T cell priming." (PMID 35740462, 2022). "We also found that LAIT upregulated the expression of tumour killing molecules Prf1, Gzmb, Ifng, Tnf, and Tnfsf10 (TRAIL) in exhausted and effector memory CD8+ and CD4+ T cells." (PMID 35808806, 2022). "Loss of YTHDF1 restores sensitivity to antitumor immunity via the recruitment of DCs, which in turn activates CD4+ and CD8+ T cells, culminating in tumor remission." (PMID 35193930, 2022).
tumor (continued). "Further experiments elucidated the capacity of A. muciniphila to increase CD4+CXCR9+ TILs and CXCR9 expression on central memory T cells in the mesenteric lymph node, to reduce the number of tumour-infiltrating Tregs, and to stimulate the production of IL-12." (PMID 35565229, 2022). "The cells involved in this individualized immunotherapy are generally CD8+ T-cells or tumor-specific CD8+T-cells, but also include CD4+ Th cells." (PMID 35804863, 2022). "As antigen-presenting cells, dendritic cells (DC) allow antigens to be recognized by CD4+ T cells and CD8+ T cells, and then CD4+ T cells transmit information to CD8+ T cells and facilitate the differentiation of effector T cells to kill tumor cells." (PMID 35662730, 2022). "In tumor samples, a significant decrease percentage of CCR5+ CXCR3− in both CD4+ and CD8+ T cells was observed (p < 0.05 and p < 0.001, respectively)." (PMID 36551555, 2022). "Globally, we detected 266 CD4+CD8+ double positive T cells out of 12,039 total cells (2.2%) analyzed with whole transcriptome scRNAseq platform, and 221 (83%) of them were from tumor, representing 4.5% of the 4,844 tumor-derived T cells." (PMID 36185254, 2022). "Our data clearly showed that the high abundance of SPINK1 corresponded with the high levels of CD4+ and CD8+ effector T lymphocytes, as well as activated dendritic and natural killer cells in the same tumor samples." (PMID 35924241, 2022). "Further, when activated CD4+ and CD8+ T cells were detected by co-staining with IFNγ, the distribution tendency was similar to that of total CD4+ and CD8+ T cells in the tumors, indicating that the TILs are activated to kill tumor cells in the TME." (PMID 36405748, 2022). "Combined treatment reduced the number of MDSCs and increased the anti-tumor DC responses and the number of IFN-γ-secreting CD4+ T cells." (PMID 35874729, 2022). "In this review, we will depict the roles and various aspects of BTN3A molecules in distinct tumor microenvironments and review how BTN3A receptors modulate diverse immune effector functions including those of CD4+ (Th1), cytotoxic CD8+ T cells, and NK cells." (PMID 36362212, 2022). "Tumors from mice treated with CTLA4-TβRII trap displayed higher proportions of 1) tumor reactive CD8+ IFNγ+ T cells, 2) CD4+ and CD8+ central memory T cells, and 3) lower percentage of FOXP3+ Tregs compared to control mice." (PMID 35577211, 2022). "Immunohistochemical staining showed that the CD4+, CD8+T cell, and macrophage infiltration levels of PD-L1-OE tumor were lower than that of the PD-L1-WT parental tumor." (PMID 35965501, 2022). "Immunochemistry and flow cytometry were used to detect the proportion of CD3+ T, CD4+ T, CD8+ T cells and activated dendritic cells (DCs) in spleens and tumor tissues to assess variation in the immune response." (PMID 35393920, 2022). "Mechanistic studies reveal that anti‐PD‐L1‐DOX‐R848‐MIP‐3α/TKNP specifically targets tumor tissue, resulting in maximum exposure of calreticulin (CRT) and HMGB1 in tumors, and significantly enhances intratumoral infiltration of CD4+ and CD8+ T cells in tumors." (PMID 37693071, 2022). "When dendritic cells sense and present tumor antigens, naive antigen-specific CD4+ and CD8+ T cells are activated, thereby mediating anti-tumor activities." (PMID 35308129, 2022). "Tumor antigens were also found to enhance the anti-tumor effects of CD8 T cells by interacting with B cells and CD4 T cells." (PMID 36569871, 2022). "Both CD8+ and CD4+ T subsets exhibit synergistic anti-tumor CAR-T activities, as CD4+ cells are conducive to developing CD8+ memory functions." (PMID 36479116, 2022). "We adopted multiplex immunofluorescence labelling of CD4+ T cells, Tregs (T regulatory cells CD4+, Foxp3+), CD8+ T cells, and B cells (B220+), at 12 weeks and ethical endpoints in the mouse APs tumours (respectively)." (PMID 36075907, 2022).
tumor (continued). "Massive infiltration of CD4+ T cells including few CD103+ CD4+ tissue resident memory T (TRM) cells and APCs surrounded Tslp-PyMttg tumor foci, while very few CD4+ T cells were detectable in the PyMttg tumors (P < 0.0001)." (PMID 35657353, 2022). "The CD4+ T cells are recognized to portray an accessory role, and CD8+ T cells are defined as cytotoxic T lymphocytes killing tumor cells." (PMID 35967384, 2022). "In the TME, MDSCs suppress CD4+ and CD8+ T cell function through PD-L1 interaction leading to the suppression of T cell activation and tumor tolerance." (PMID 35205732, 2022). "FPS increased the number of macrophages, CD4+, and CD8+ T cells in the spleen of Hepa1-6 tumor-bearing mice, indicating FPS had immune-improving functions." (PMID 35662730, 2022). "Tumor-infiltrating lymphocytes (TILs) are composed of CD8+T cells, CD4+T cells, regulatory T cells, macrophages, neutrophils, myeloid suppressor cells and natural killer cells, which interact with each other and play an anti-tumor or pro-tumor effect." (PMID 35835721, 2022). "On that day, the greatest influx of CD4+ and CD8+ effector cells into the tumor tissue after DC-based vaccines administration was observed." (PMID 35372586, 2022). "Meanwhile, one investigator found in a mouse model that CXCL9 expressed by tumor cells suppressed local tumor growth and metastasis by recruiting host NK cells and a large number of CXCR3+CD4+ and CXCR3+CD8+ host T cells." (PMID 36479091, 2022). "Most interestingly, an unsupervised clustering analysis of IC co-expression on CD4+ and CD8+ TILs identified two tumor subgroups, named IChigh and IClow." (PMID 36077799, 2022). "The EMT statuses of the patients were highly correlated with a low density of tumor-infiltrating CD3-, CD4-, and CD8-positive lymphocytes." (PMID 35145164, 2022). "Antitumor CD4+ T cells and CD8+ cells are indispensable for the human adaptive system and their anti-tumor function relies on aerobic glycolysis." (PMID 36319992, 2022). "CD4+ central memory T (TCM) cells maintain immune memory and play a protective role in tumor metastasis." (PMID 35422890, 2022). "An increasing body of evidence suggests that the activation of immune cells, such as CD4, CD8, and NK cells, can kill tumor cells via molecular mechanisms." (PMID 36091935, 2022). "Excitingly, we identified enhanced immunological response after conjugate irradiation which resulted in the attraction and activation of CD4+ and CD8+ T cells in PIT-treated tumours compared to the control group." (PMID 35057796, 2022). "The vast majority of tumour-infiltrating cells comprise cytotoxic CD8+ and helper CD4+ T cells, but also include a minority of B lymphocytes and natural killer cells." (PMID 35350071, 2022). "The inhibition of circPTPN22 suppresses tumor cell growth in vivo, and induces immune cell infiltration, (CD8+ T cells, CD4+ T cells, γδT cells, and NK cells)." (PMID 35186039, 2022). "It is important to note that the CD4-IL2RAhi- and CD4-IL2RAhi-CCL22+-Treg subtypes were already present in the pre-NACT tumors and persisted in all residual tumor samples after NACT therapy." (PMID 35907904, 2022). "A post treatment tumor specimen obtained from our NC patient at day 98 revealed (i) a partial necrosis, (ii) a switch from a CD3+CD4+ dominant to a CD3+CD8+ dominant lymphocyte infiltrate as well as (iii) an increased number of tumor infiltrating macrophages." (PMID 36387105, 2022). "(A–D) The treated (right side) and untreated tumors (left side) were harvested at the end of the experiment and analyzed for the CD8+/CD4+ ratio (A) and the frequency of CD8+ (B), CD8+ CXCR4+ (C), and CD8+ CXCR3+ (D) in the tumor microenvironment (TME)." (PMID 35314027, 2022). "M2 polarization prevents the production of cytokines required to support tumor-specific CD8+ T, CD4+ Th1, and Th17 cells and promotes the function of tumor-supportive CD4+ regulatory T cells." (PMID 35729639, 2022).
tumor (continued). "Our results showed that CD4+ and CD8+ T cells and their respective subsets were closer to the tumor cells in the IM region." (PMID 36685566, 2022). "Delta-24-RGD treatment was demonstrated to remodel the tumor microenvironment, predominantly through enhanced CD8+ and CD4+ T cell infiltration in the tumor." (PMID 35740589, 2022). "PLGA nanoparticles have been designed for the transportation of cytokine agonists, siRNAs, or CpG-coated tumor antigens to enhance antigen uptake by DCs and trigger both CTL (CD8+) and Th (CD4+) immune responses." (PMID 35214129, 2022). "In the next step, these processed antigens are presented to specific CD4+ and CD8+ T cells, ultimately triggering anti-tumor responses." (PMID 36300095, 2022). "High percentages of post-operative peripheral CD3(+), CD4(+), and CD8(+) T cells predict lower recurrence free survival in patients with CRC as they exert anti-tumor functions." (PMID 35185893, 2022). "We also labeled CD4 and CD8 lymphocytes in IE and INE tumor samples to characterize the infiltrating cells." (PMID 36358618, 2022). "Our results showed that TS not only effectively increased the ratio of CD4+ T cells in the spleen of tumor bearing mice, but also elevated the infiltration of CD4+ and CD8+ T cells in tumor tissues." (PMID 35577774, 2022). "We found that LPAR2 expression had a positive correlation with tumor purity in HNSC and KIRC, the infiltration of B cells and CD4 + T cells in HNSC, and the infiltration of B cells, CD4 + T cells, neutrophils, and DCs in KIRC." (PMID 35241179, 2022). "NRP1 is a marker for CD4+ regulatory T cells, is sometimes coexpressed with PD-1 on a subset of CD8 tumor-infiltrating T lymphocytes, and inhibits T cell antitumor immunity." (PMID 36131795, 2022). "Vaccines with little synergistic effect or unmanageable elicitation of the CD4+ and CD8+ T cell immunity usually fail to induce a potent and durable anti-tumor protection." (PMID 35547749, 2022). "In this study, the group demonstrated increased tumor rejection in mice treated with anti-CD25 antibodies, which depleted CD4+CD25+ Tregs in mice." (PMID 34417572, 2022). "Dendritic cells (DCs), which work as antigen-presenting cells (APC), have the potential to activate CD4+ and CD8+ T cells to induce tumor-specific response in CC." (PMID 36324514, 2022). "Single sections underwent multiplexed immunofluorescence staining for immune cell markers (CD45, CD3, CD4, CD8, FOXP3, PD1) and tumor/cell segmentation markers (DAPI, pan-cytokeratin, AE1, NaKATPase, and S6)." (PMID 34732839, 2022). "Tumor-reactive IFN-γ–secreting T cells were detected in pool 1, and the reactive cells were enriched in the DP CD4+ Th TIL subset." (PMID 35439168, 2022). "These cells can actively suppress the proliferation of CD4+ and CD8+ T lymphocytes that would otherwise recognize tumor antigens." (PMID 35330159, 2022). "First, the “Gene” module analysis revealed that BTN3A2 expression is remarkably positively correlated with invading levels of tumor purity, B cells, dendritic cells, CD8+ T cells, macrophages, neutrophils, and CD4+ T cells in LUAD." (PMID 35873496, 2022). "Cellular immunity mediated by T-lymphocytic subsets such as CD4+ T and CTL is an important way for the body to eliminate the threat of tumor cells." (PMID 35386701, 2022). "The anti-cancer mechanisms reported to be associated with TLR-8-mediated activation of mDC include promoting the activation of tumor-specific CD8+ T cells, skewing CD4+ T cell responses towards Th1, and inhibiting Treg function." (PMID 36297510, 2022). "To illuminate which T cell subsets were indispensable to the combined therapy-mediated tumor regression, we depleted CD4+/CD8+ T cells in mice using CD4/8 antibodies, respectively." (PMID 36544785, 2022).